INS (insulin)
Diseases named in the same sentence as INS in open-access papers (continued):
Sharing a sentence is not in itself a finding about the gene and the disease.
Insulin resistance (continued). "However, HFS improved insulin resistance compared with HF (P < 0.05), and HOS showed a drastic reduction of plasma insulin and fasting blood glucose levels in HO (both P < 0.001)." (PMID 33318479, 2020). "Nevertheless, there are available methods such as homeostatic model assessment of insulin resistance (HOMA-IR), homeostatic model assessment 2 (HOMA2), the quantitative insulin sensitivity check index (QUICKI), or Matsuda, which are generally accepted and considered reliable." (PMID 32545342, 2020). "According to a study, almost one-third women with GDM had insulin secretion defects without severe insulin resistance, one-half had predominant serious insulin resistance without insulin secretion defects, and less than 20% had both defects." (PMID 32184821, 2020). "This absence of hyperglycemia in Napepld∆Hep mice indicated that these mice were not yet strongly resistant to insulin despite their increased insulin resistance index under control diet." (PMID 32443626, 2020). "Emerging evidence indicates a pivotal role of LTB4 in insulin resistance and hepatic steatosis, with LTB4 directly enhancing macrophage chemotaxis, reducing insulin-stimulated glucose uptake in myocytes, and inhibiting insulin-mediated suppression of hepatic glucose output." (PMID 32973519, 2020). "It is known that both increased insulin resistance and inadequate insulin secretion contribute to hyperglycemia in nonpregnant women in varying degrees, and their roles in GDM are also different." (PMID 32184821, 2020). "There are tissue-specific differences in PCOS-related insulin resistance, with skeletal muscle and myotubes derived from women with PCOS demonstrating insulin resistance and decreased insulin responsiveness, as well as adipocytes with impaired insulin sensitivity but normal responsiveness." (PMID 33113794, 2020). "At the same time, lower mitochondrial ROS level, higher mitochondrial membrane potential, and attenuated insulin resistance were observed in HFD rats following exercise intervention, which confirmed the role of Mfn2 in exercise-induced improvement in insulin sensitivity." (PMID 33339212, 2020). "Testosterone (p < 0.001), HDL (P < 0.002), CRP (p < 0.001) were higher in the Middle Eastern population, whilst glucose, WCC, insulin and insulin resistance no longer differed between the 2 cohort of PCOS women." (PMID 33144665, 2020). "Estimates for both insulin resistance (HOMA-IR) and insulin secretion (HOMA-b) improved." (PMID 31952273, 2020). "Similarly, inappropriately increased activation of p38 MAPK has been suggested to contribute to insulin resistance by downregulating the expression of the insulin-responsive glucose transporter (GLUT4) and, in turn, reducing insulin-stimulated glucose uptake." (PMID 33322742, 2020). "Interestingly, tissue-specific indices of insulin resistance (adipose, liver and muscle) all ranked better (i.e. were more informative), than HOMA-IR or individual fasting or insulin levels." (PMID 32514005, 2020). "However, when adipose tissue becomes resistant to the action of insulin, FFA concentrations rise in circulation and play an important role in the development of insulin resistance." (PMID 32849302, 2020). "Equally, impaired insulin signaling may further lead to elevated ceramide levels and ceramide-induced activation of atypical PKC, which aggravates insulin resistance." (PMID 33329397, 2020). "We showed that LA in contrast to PA does not induce neuronal insulin resistance, but in combination with cholesterol can even enhance insulin signaling." (PMID 32456175, 2020). "Concurrently, these mice exhibited an increase in leptin, nonesterified fatty acid (NEFA), insulin, and glucose in plasma, coupled with glucose intolerance and insulin resistance." (PMID 32351670, 2020).
Insulin resistance (continued). "Fasting insulin concentration was on the upper end of the normal range in our laboratory (<19.5 mU/L), resulting in average HOMA-IR values over 2, indicating the presence of some degree of insulin resistance." (PMID 33066107, 2020). "Secondly, insulin resistance plays an important role in developing NAFLD among the nonobese, but insulin levels and insulin resistance were not examined in the initial study." (PMID 32411195, 2020). "Insulin resistance is commonly present in EMS, although there has been some debate as to whether that is always true and if alternative routes by which insulin dysregulation may develop exist." (PMID 33233816, 2020). "In addition, macrophage-specific JNK1/2-null mice on a high fat diet were protected from insulin resistance, as seen by elevated AKT activation in insulin-sensitive tissues, as compared to wild-type mice on the same diet." (PMID 32183037, 2020). "The sucrose group had elevated fasting insulin (P=0.018), Homeostatic Model Assessment for Insulin Resistance (HOMA-IR) (P<0.001) and TyG index (P<0.001) values, and markedly reduced quantitative insulin check index (QUICKI) (P=0.002) and hepatic insulin sensitivity (HIS) (P=0.003) indices." (PMID 32086249, 2020). "Additionally, NV-LJ3402 administration reduced glucose and insulin levels in the plasma and resulted in a slight improvement in glucose tolerance, indicating that NV-LJ3402 reduces lipid accumulation and insulin resistance in HFD mice." (PMID 33086627, 2020). "VAT ANGPTL4 levels correlated negatively with high-density lipoprotein (HDL) cholesterol (r = −0.24; p = 0.048) and positively with fasting serum insulin (FSI) (r = 0.51; p= 0.008) and Homeostatic Model Assessment for Insulin Resistance (HOMA-IR) (r = 0.43; p = 0.029)." (PMID 33003532, 2020). "In addition, increased MSI2 DNA methylation was positively correlated with increased insulin sensitivity (QUICKI) and decreased insulin resistance (HOMA-IR)." (PMID 32653024, 2020). "Contrary to these findings, 12 weeks of dietary NR supplementation did not alter the insulin sensitivity, whole-body glucose metabolism, β-cell insulin secretory capacity, and gut incretin hormone secretion in obese men with insulin resistance." (PMID 32143417, 2020). "The ability of AgRP neurons to induce insulin resistance depends on the expression of NPY, and the application of NPY in the CNS has been shown to efficiently reduce sympathetic activation of BAT and improve systemic insulin sensitivity." (PMID 33123166, 2020). "In addition, plasma SFA maintains a state of insulin resistance (enhance HOMA-IR) by promoting the accumulation of lipid derivatives, such as the synthesis of ceramides that inhibit intracellular insulin signaling, principally in skeletal muscle." (PMID 32962299, 2020). "Within the NMRI control strain insulin resistance increased and insulin sensitivity decreased slightly but not significantly, reflecting the natural adaptation during pregnancy." (PMID 32374082, 2020). "Indices for BCF and insulin sensitivity were highest among NGT individuals (representing good BCF and insulin sensitivity) and lowest among T2D individuals (representing impaired BCF and insulin resistance)." (PMID 31486878, 2020). "Data are also limited regarding indices of insulin resistance as circulating insulin or HBA1C were not systematically assessed." (PMID 32655494, 2020). "Solving this mystery is important because a similar state of adipose tissue “selective insulin resistance” in which insulin-stimulated glucose uptake, but not AKT activity per se, is defective, occurs in several models of adipocyte insulin resistance." (PMID 31996678, 2020). "Insulin resistance resulting from caffeine consumption was also evident in examination of the ISI that calculates whole body insulin sensitivity, through OGTT-derived glucose and insulin levels." (PMID 33339359, 2020).
Insulin resistance (continued). "The strong link between insulin requirement and fasting and multiple OGTT abnormalities could, therefore, be explained by the presence of insulin resistance." (PMID 32987806, 2020). "Tadalafil as an inhibitor of PDE5 enhanced cGMP-dependant insulin secretion and improved β cell function, also in the metabolic syndrome, but no overall improvement in insulin resistance was observed." (PMID 33153226, 2020). "Although adipose tissue itself does not play a dominant role in insulin-dependent glucose uptake, it seems to have a paramount role in inducing systemic insulin resistance resulting from obesity." (PMID 32375231, 2020). "In addition, the insulin-sensitizing drug metformin can improve menstrual disorder, promote ovulation, and elevate birth rate in PCOS, especially when accompanied by insulin resistance." (PMID 32757043, 2020). "Reduced insulin sensitivity and signaling at synapses has been observed after TBI in animal studies, indicating that insulin resistance may occur and impair the body’s ability to maintain glucose homeostasis." (PMID 33100956, 2020). "Second, in Bjornstad's study, insulin sensitivity was evaluated by the gold standard multiphase hyperinsulinemic euglycemic clamping test, and metformin was found to improve insulin resistance regardless of baseline BMI, weight, fat mass, and insulin dose." (PMID 33457425, 2020). "Whereas iron profile, insulin, and insulin resistance were not significantly different among the two groups as assesses by the Mann-Whitney U test." (PMID 33520544, 2020). "Insulin stimulation also prompted glucose uptake in podocytes, as demonstrated by uptake of the glucose analogue 2-NBDG, and this response was reduced upon palmitate induced insulin resistance." (PMID 33458251, 2020). "Lastly, as insulin resistance was not assessed, it cannot be excluded that the horses of either of the groups were less sensitive to insulin, while dysregulated to a similar extent." (PMID 32448298, 2020). "Given that FGF21 has been shown to be elevated in obesity, and in particular in subjects with insulin resistance, the notion that FGF21 levels would become even further elevated following RYGB surgery, a procedure which rapidly improves insulin sensitivity, represents a paradox." (PMID 32158768, 2020). "During insulin resistance (IR), insulin is no longer able to suppress lipolysis and this results in a chronically high flux of FFAs to the liver and this is considered to be one of the main drivers of NAFLD." (PMID 33597924, 2020). "Brain insulin resistance has negative effects on peripheral insulin sensitivity as this condition impairs brain-derived signals that improve metabolism in peripheral tissues." (PMID 33047031, 2020). "Fourthly, insulin levels, insulin resistance, and waist to height ratio (WHtR) were not assessed in this study." (PMID 32973687, 2020). "Regarding insulin resistance, changes in fasting insulin and HOMA-IR were not significantly different between the two groups." (PMID 32025522, 2020). "The most likely reason for higher glucose concentrations is insulin resistance, but that cannot be confirmed in this study due to the fact that the measurement of insulin and insulin tolerance test were not performed." (PMID 32947606, 2020). "In addition, the Middle Eastern normal population had increased insulin levels and HOMA IR compared to the UK population, suggesting that they had an inherent increased insulin resistance despite their BMI and age being well matched." (PMID 33144665, 2020). "In spontaneously hypertensive rats, the glucose levels were not affected by dLAN, but already high plasma insulin levels were even more aggravated after exposure to dLAN, suggesting that dLAN can deepen insulin resistance at least in this animal model." (PMID 32751870, 2020).
Insulin resistance (continued). "Insulin resistance drives increases in serum insulin during mid-pregnancy, reflected by increases in the homeostatic model assessment of insulin resistance (HOMA-IR), and decreases in the quantitative insulin-sensitivity check index (QUICKI)." (PMID 32215823, 2020). "In addition, the exercise intervention elicited beneficial changes in biochemical markers such as decreased fasting insulin, total- and LDL-cholesterol levels, and ameliorated insulin resistance." (PMID 32616883, 2020). "In insulin and fat function studies, triglyceride-glucose index (TGI) was used as a surrogate for identifying insulin resistance among healthy subjects, and visceral adiposity index (VAI) was identified as an indicator of visceral adipose function and insulin sensitivity." (PMID 33081173, 2020). "In particular, the adipokines resistin, leptin, PAI-1, and retinol binding protein 4 (RBP4) induce insulin resistance in megakaryocytes by interfering with IRS-1 expression with a negative impact on insulin signaling in platelets." (PMID 31963572, 2020). "Indeed, high insulin levels have been shown to enhance BCAA uptake in the liver of obese rats and promote further severe liver insulin resistance by the attenuation of Akt2 signaling via mTORC1- and mTORC2-dependent pathways." (PMID 32823827, 2020). "Moreover, in rats with insulin resistance that had been induced by a high-fat diet (HFD), memory performance was impaired and the effect of hippocampal application of insulin was blunted." (PMID 32789766, 2020). "PEPD attenuated insulin-induced AKT2 phosphorylation, resulting in increased insulin resistance." (PMID 32722593, 2020). "It is also true that insulin resistance is a precursor for T2DM, and insulin activity may be subject to genetic variance at several loci." (PMID 32685554, 2020). "TRIB3 is coupled to insulin resistance in oxidative stress, antioxidant stress, inflammation, adiponectin actions, peroxisome proliferator-activated receptor (PPAR) actions, SIRT1 actions, and insulin signal transduction." (PMID 33192545, 2020). "Insulin resistance is an insulin dysfunction, in which insulin receptors do not function properly, which inactivates downstream components of the insulin pathway such as insulin receptor substrate (IRS)." (PMID 32575897, 2020). "Certain of these studies suggest that in insulin‐resistant states, the VMH glucose‐sensing apparatus in vivo could be altered in a manner that may facilitate insulin resistance, as previously suggested." (PMID 32704560, 2020). "Previous studies have shown that blood glucose in some overweight or obese patients did not adequately decrease during ITTs, due to insulin resistance, thus repeated doses of insulin need to be administered." (PMID 32328036, 2020). "Evidence suggests that, by targeting insulin-sensitive cells, PDE5 inhibition may contribute to the improvement of insulin resistance; in particular, in skeletal muscles, adipocytes, hepatocytes, and endothelial cells." (PMID 32774364, 2020). "This condition closely simulates the phenotype of nonobese Asian T2D as they have less insulin resistance (not to the same extent as in obese patients) and disproportionally reduced insulin secretion, as compared with obese patients with T2D (white patients)." (PMID 33103024, 2020). "The intervention did not affect fasting insulin levels in this sample of children, although previous investigations have reported effects of physical activity interventions on insulin and on insulin resistance." (PMID 32501613, 2020). "Although disease development differs from the slow-onset of DM type 2 in humans, this approach produces sustained hyperglycemia without insulin dependency and results in progressive insulin resistance." (PMID 32100119, 2020).
Insulin resistance (continued). "They found that the serum OC level was significantly and directly correlated with insulin secretion and insulin resistance, but the serum OC level was not significantly different between women with GDM and healthy pregnant women." (PMID 33911828, 2020). "However, the serum levels of insulin increased in the HL group, and tri-tea partially prevented the increase in serum insulin in the HLT mice, improving insulin resistance." (PMID 32348424, 2020). "Dietary changes and exercise, in addition to drug therapy (metformin with or without insulin), have been the mainstay with the clinical aim of reducing insulin resistance." (PMID 32018348, 2020). "Importantly, RAGE knockdown also improved hyperglycemia, and insulin resistance in aged C57BL/6 mice with steatosis, as revealed by glucose and insulin tolerance tests." (PMID 32936538, 2020). "Eight studies reported no changes in glucose profiles (fasting blood glucose and insulin), six studies reported reductions in fasting blood glucose, Homeostatic Model Assessment for Insulin Resistance (HOMA-IR) values, and insulin levels." (PMID 33266002, 2020). "Probiotic and synbiotic supplementation had beneficent effects in T2DM by improving glycated hemoglobin (HbA1c), fasting insulin levels, Homeostasis model of assessment-insulin resistance (HOMA-IR), and the quantitative insulin sensitivity check index (QUICKI)." (PMID 32760408, 2020). "Notably, this further stresses the usefulness of tissue-specific indicators of insulin resistance, relative to more general indicator such as HOMA-IR or fasting glucose/insulin levels." (PMID 32514005, 2020). "Based on insulin resistance research, considering the insulin secretion response to food choices rather than simply thinking about the increase and decrease in blood glucose is likely to be beneficial for reproductive medicine." (PMID 32684824, 2020). "The revised QUICKI takes into account fasting serum nonesterified fatty acid levels, in addition to plasma glucose and serum insulin, and has better discriminatory power, particularly in nonobese individuals who present with mild insulin resistance." (PMID 31425580, 2020). "At 2 months of age, db/db mice were dramatically obese (+66% in body weight) and displayed severe hyperinsulinemia (+6-fold in nonfasted blood insulin) and hyperglycemia (+2.6-fold in nonfasted blood glucose), indicative of severe insulin resistance." (PMID 33148881, 2020). "Insulin resistance is estimated by ITT and it could be a useful tool for predicting the effectiveness of insulin sensitizers." (PMID 32987623, 2020). "Barriers to this include adult cutoffs or a single set of cutoff points across all age groups, lack of normative data for plasma insulin level, pubertal insulin resistance, and lack of central obesity (waist) cutoff points in majority of the study settings." (PMID 32296710, 2020). "Women in the higher tertile of adherence to the unhealthy dietary pattern had a higher homeostatic model assessment for insulin resistance (HOMA) index (b = 2.49; 95% CI: 0.41–4.57; p = 0.02) and circulating insulin (b = 4.52; 95% CI: 0.44–8.60; p = 0.03) than the women in the lowest tertile." (PMID 32098332, 2020). "However, they are deemed to be associated, at least in part, with women being spared from the insulin-desensitizing effects of myocellular accumulation of ceramide, which protects them from FFA-induced insulin resistance." (PMID 32354182, 2020). "Second, we measured insulin sensitivity using HOMA-IR and ISIOGTT obtained from OGTT, whereas the hyperinsulinemic-euglycemic clamp technique is considered the most reliable method available for estimating insulin resistance and is used as reference standard." (PMID 33349270, 2020). "In addition, the insulin resistance index (HOMA-IR) and quantitative insulin sensitivity check index (QUICKI) were calculated." (PMID 30941040, 2019).